NEDD9 (neural precursor cell expressed, developmentally down-regulated 9)
Diseases named in the same sentence as NEDD9 in open-access papers (continued):
Sharing a sentence is not in itself a finding about the gene and the disease.
pulmonary arterial hypertension (2 papers, 2023 to 2024). Pulmonary arterial hypertension (PAH) is a group of diseases characterized by mean pulmonary artery pressure >20 mmHg and elevated pulmonary arterial resistance leading to right heart failure. "Indeed, Nedd9 inhibition has been shown to prevent pulmonary arterial hypertension (PAH) in Nedd9-deficient transgenic mice." (PMID 36835058, 2023). "The authors also show that pulmonary hypertension and vascular fibrosis are attenuated by inhibition of NEDD9, further confirming our findings that NKX2-5 is a critical regulator of vascular remodeling." (PMID 38652537, 2024).
acute lymphoblastic leukemia (1 paper, 2017). Leukemia with an acute onset, characterized by the presence of lymphoblasts in the bone marrow and the peripheral blood. "In contrast, NEDD9 mediates dissemination in BCR-ABL-dependent acute lymphoblastic leukemia (ALL) showing splenomegaly by accumulation of and pre-B cell lymphoblasts." (PMID 29100287, 2017).
adult T-cell leukemia (1 paper, 2017). "In the same venue, in adult T-cell leukemia (ATL), the NEDD9 overexpression is induced by the Tax oncoprotein of the HTLV1 virus and enhances lymphocyte motility." (PMID 29100287, 2017).
atherosclerosis (1 paper, 2013). A disease characterized by the build-up of fatty material and calcium deposition in the arterial wall resulting in partial or complete occlusion of the arterial lumen. "We identified five novel interactions that are not evident from marker-based interaction testing and successfully replicated one of these interactions, between SMAD3 and NEDD9, in an independent sample from the Multi-Ethnic Study of Atherosclerosis." (PMID 23468652, 2013). "One interaction between SMAD3 and NEDD9 on HDL-C was further replicated in an independent sample from the Multi-Ethnic Study of Atherosclerosis." (PMID 23468652, 2013). "One of these suggestive gene-level interactions, between SMAD3 and NEDD9 on the levels of HDL-C, is significantly replicated in an independent cohort from the Multi-Ethnic Study of Atherosclerosis (MESA)." (PMID 23468652, 2013).
breast adenocarcinoma (1 paper, 2012). "However, analyzing genes and proteins expressed in MCF-7 breast adenocarcinoma cells upon activation of the ErbB receptor with its ligand heregulin, NEDD9 emerged as one of only five hits upregulated and hyperphosphorylated in both transcriptome and proteome datasets." (PMID 23226728, 2012).
chronic lymphocytic leukemia (1 paper, 2022). "We show that global or B-cell-specific deletion of Nedd9 in chronic lymphocytic leukemia (CLL) mouse models delayed CLL development, markedly reduced disease burden and resulted in significant survival benefit." (PMID 35523865, 2022).
COVID-19 (1 paper, 2025). A disease caused by infection with severe acute respiratory syndrome coronavirus 2. "Although the study does not clearly articulate the specific mechanism of action between NEDD9 and severe acute respiratory syndrome coronavirus 2 (SARS CoV-2), which causes COVID-19, it provides a direction for further research into the relationship between NEDD9 and the virus." (PMID 40266966, 2025).
dental caries (1 paper, 2025). The decay of a tooth, in which it becomes softened, discolored, and/or porous. "Genetic variation at rs7738851 on NEDD9 influenced susceptibility to dental caries in permanent teeth, whereas rs1594318 within ALLC on 2p25 was associated with dental caries in primary teeth." (PMID 41444670, 2025).
esophageal cancer (1 paper, 2021). A primary or metastatic malignant neoplasm involving the esophagus. "We first confirmed NEDD9 expression in human esophageal cancer cell lines (KYSE70, KYSE150, KYSE450, KYSE510, and EC9706)." (PMID 33710809, 2021).
gram-negative bacterial infections (1 paper, 2025). Infections caused by bacteria that show up as pink (negative) when treated by the gram-staining method. "In summary, our study suggests that the downregulation of NEDD9 in macrophages serves as a host defense mechanism against Gram-negative bacterial infections." (PMID 40506423, 2025).
Hepatic fibrosis (1 paper, 2020). The presence of excessive fibrous connective tissue in the liver. "NEDD9 plays a role in the TGF-β pathway and growth signals initiating cellular proliferation and has been identified as upregulated in hepatic fibrosis." (PMID 32158398, 2020).
hepatoblastoma (1 paper, 2024). Hepatoblastoma (HB) is a malignant hepatic tumor and is the most common pediatric liver cancer. "We first confirmed the association of NEDD9, FAK, and AKT signaling in HepG2 cells, a hepatoblastoma cell line." (PMID 38619434, 2024). "The correlation between NEDD9 and p-FAK and p-AKT was more clearly shown in a hepatoblastoma-derived cell line (HepG2 cells)." (PMID 38619434, 2024).
Hypertension (1 paper, 2014). The presence of chronic increased pressure in the systemic arterial system. "Recent studies have linked the function of both PTK2B and NEDD9 to vascular integrity, angiogenesis, and hypertension." (PMID 25594051, 2014). "Finally, one recent GWAS study has linked NEDD9 to primary open angle glaucoma (POAG), a disease that could be caused by endothelial defects or hypertension." (PMID 25594051, 2014).
influenza (1 paper, 2025). An acute viral infection of the respiratory tract, occurring in isolated cases, in epidemics, or in pandemics; it is caused by serologically different strains of viruses (influenzaviruses) designated A, B, and C, has a 3-day incubation period, and usually lasts for 3 to 10 days. "However, the knockdown of NEDD9 decreased the expression of influenza protein NP." (PMID 40266966, 2025).
leiomyoma (1 paper, 2014). A well-circumscribed benign smooth muscle neoplasm characterized by the presence of spindle cells with cigar-shaped nuclei, interlacing fascicles, and a whorled pattern. "DUSP1, IGFBP6 and NEDD9 were down-regulated in the majority of leiomyomas compare to matched normal tissues in accordance with microarray data." (PMID 25268745, 2014).
liver tumors (1 paper, 2024). "Therefore, the upregulation of Nedd9 expression in the liver might be related to its increased levels in hepatocytes, which are potentially linked to the development of liver tumors." (PMID 38619434, 2024).
lung squamous cell carcinoma (1 paper, 2023). "Moreover, NEDD9, MRPL21, SNRPF, and SCLT1 genes were identified to be involved in lung squamous cell carcinoma drug sensitivity/resistance." (PMID 37185598, 2023).
lymphocytic leukemias (1 paper, 2022). "Although NEDD9 was designated to be the lymphocyte-specific member of the CAS family, the role of NEDD9 in lymphocytic leukemias has remained unexplored." (PMID 35523865, 2022).
metastatic disease (1 paper, 2022). "First, NEDD9 as a member of CAS-family proteins, mechanistically interacts with numerous SRC-family kinases to phosphorylate various downstream proteins, most of which have been studied in the context of metastatic disease." (PMID 35626121, 2022).
muscle atrophy (1 paper, 2025). The loss of muscle tissue due to inactivity or disease. "Conversely, these findings imply that activation of the NEDD9‐FAK signalling pathway may represent a potential therapeutic strategy for the treatment of muscle atrophy." (PMID 40641186, 2025).
Obesity (1 paper, 2022). Accumulation of substantial excess body fat. "NEDD9 was found to regulate the developing embryonic nervous system, and HIVEP1 was involved in the obesity of newborns." (PMID 36685960, 2022).
periodontitis (1 paper, 2026). An acute or chronic inflammatory process that affects the tissues that surround and support the teeth. "Notably, the down-regulation of miR-1260b, miR-1224-5p, miR-3156-5p and miR-4286 may contribute to the progression of periodontitis by promoting the expression of NEDD9, P2RX5 and CSF1R." (PMID 41992052, 2026).
small cell lung carcinoma (1 paper, 2022). Small cell lung cancer (SCLC) is a highly aggressive malignant neoplasm, accounting for 10-15% of lung cancer cases, characterized byrapid growth, and early metastasis. "Another work demonstrated that the inhibition of autophagy sensitizes small cell lung cancer cells to cisplatin treatments, in part by downregulating NEDD9 expression." (PMID 35626121, 2022).
synovial sarcoma (1 paper, 2020). "Expression of Fgfr1 and Nedd9, also located near common integration sites, did not accelerate synovial sarcoma development." (PMID 32019274, 2020).
cancer (77 papers, 2008 to 2025). A tumor composed of atypical neoplastic, often pleomorphic cells that invade other tissues. "Both overexpression and loss of NEDD9 function have been found to be tumor-promoting in different cancers, likely because either form of disruption of its role as a scaffold impairs downstream processes." (PMID 35626121, 2022). "The scaffold protein NEDD9 is frequently upregulated and hyperphosphorylated in cancers, and is associated with poor clinical outcome." (PMID 35523865, 2022). "As part of the Crk-associated substrate (CAS)family, NEDD9 is upregulated in multiple cancer types and participates in the adhesion and migration of cancer cells and tumour invasion." (PMID 36776356, 2022). "Elevated NEDD9 expression has been reported in many cancer types and is typically associated with tumor growth and invasion." (PMID 34314382, 2021). "Overexpression of NEDD9 has now been strongly linked to poor prognosis in various types of cancers, as well as resistance to first‐line chemotherapeutics." (PMID 34432355, 2021). "It has been documented that NEDD9 is strongly associated with development of multiple types of cancer." (PMID 31019460, 2019). "Growing evidence suggests that overexpression of NEDD9 can increase the risk of metastasis of cancer cells." (PMID 31019460, 2019). "In this study, we found that aberrant NRP-1 expression was positively associated with enhanced levels of NEDD9, a protein linked with increased metastases in multiple human cancers." (PMID 26701889, 2016). "We note that NEDD9 has been implicated in cellular migration as well as in the invasion and metastasis of cancer cells, and that unregulated ASNS expression has also been linked with cancer." (PMID 24554596, 2014). "Currently, it is believed that NEDD9 protein is associated with migration, invasion and metastasis of cancer cells." (PMID 24058594, 2013). "Overexpression of the NEDD9 protein has been strongly linked to poor prognosis and increased metastasis in cancer, as well as resistance to first-line chemotherapeutics in multiple tumor types." (PMID 23226728, 2012). "This positive correlation between NEDD9 expression and metastasis occurrence has also been widely reported in cancer and further underlines the role of this molecule in the metastatic process." (PMID 23226728, 2012). "Indeed, in many human cancer entities NEDD9 upregulation is associated with tumor aggressiveness, metastasis and resistance to chemotherapy." (PMID 40506423, 2025). "Thus, the Crk-associated substrate family member NEDD9 is implicated in the adhesion, migration, invasion, and epithelial–mesenchymal transition of cancer cells as E-cadherin." (PMID 38137332, 2023). "NEDD9 is rarely mutated, but frequently shows elevated expression in cancer." (PMID 31462898, 2019). "NEDD9 is currently studied for its association with the progression of cancer, and studies have shown that NEDD9 is elevated in the plasma of patients after SARS-CoV-2 infection, so we speculated whether NEDD9 is related to the replication process of influenza viruses." (PMID 40266966, 2025). "Due to its multiple roles in cancer progression, NEDD9 has been proposed as a potential therapeutic target." (PMID 40362444, 2025). "Our studies have also demonstrated that NEDD9 positively regulates angiogenesis, an essential factor in cancer progression." (PMID 40362444, 2025). "In cancer, NEDD9 overexpression enhances cell migration by promoting focal adhesion turnover; activates proliferative signal pathways; and contributes to genomic instability." (PMID 40362444, 2025). "In most cancer cells, NEDD9 promotes biological events such as migration, invasion, epithelial mesenchymal transition (EMT) and chemotaxis." (PMID 40506423, 2025). "Although mostly studied for its role in cancer, NEDD9 has been shown to alter lymphocyte trafficking in secondary lymphoid organs, suggesting a role for NEDD9 in regulating immune responses." (PMID 40506423, 2025).
cancer (continued). "NEDD9 expression is altered in a number of clinical conditions such as cancer, but its role in innate immunity against infections remains elusive." (PMID 40506423, 2025). "NEDD9 is elevated in HER2+ cancers and correlates with resistance to anti-HER2 therapy and low relapse free survival (RFS) rates, post-treatment." (PMID 36831460, 2023). "Over nearly two decades ago, altered expression of the NEDD9 was identified as a contributing factor to cancer metastasis in many different kinds of cancer." (PMID 36604412, 2023). "Further clinical research is needed to utilize benign biopsies to evaluate NEDD9 as a potential biomarker of disease progression in clinical settings, which could enable early diagnostics and the identification of patients at high risk for cancer at early stages." (PMID 36831460, 2023). "Overall, these results suggest that NEDD9 plays a crucial role in luminal cell proliferation and expansion of the ductal compartment, which is a primary source of human cancer." (PMID 36831460, 2023). "To evaluate our findings in the context of human cancer, we analyzed the expression of NEDD9 in multiple HER2+ human breast cell lines." (PMID 36831460, 2023). "Previously, it was shown that the deletion of NEDD9 in mouse models of HER2 cancer interferes with tumor growth, but the role of NEDD9 upregulation is currently unexplored." (PMID 36831460, 2023). "Several genes associated with cancer cell motility, including SEMA5A, PDGFRB, TGFB2, CXCR4, SNAI1, ICAM1, and NEDD9, were decreased in shGPR81 cells." (PMID 35428832, 2022). "Altered NEDD9 expression accompanies and promotes metastasis in a large number of cancers, including NSCLC." (PMID 35626121, 2022). "NEDD-9 is acting as pro-metastatic stimulus in a several cancer types changing tumor microenvironment by influencing cell attachment, migration, invasion, cell cycle, apoptosis, and oncogenic signal transduction." (PMID 33485292, 2021). "Among these target genes, KLK9, WNT3A, FGF18, FIBP, SOX12, TGFBI, and NEDD9 have been reported to participate in the development of human cancers." (PMID 33344223, 2020). "Baicalein, a flavone derived from RS, has been reported to inhibit cancer cell metastasis via inactivation of the TGFβ-SMAD pathway and inhibit cancer cell proliferation via suppression of NEDD9 expression in cells." (PMID 33273910, 2020). "Upregulation of NEDD9 is reported to activate Rac1 GTPase and drive mesenchymal-mode movement of cancer cells." (PMID 31019460, 2019). "Recent studies have shown that NEDD9 is involved in the control of cancer cell mesenchymal-mode movement in three-dimensional environments by affecting the Rac1 signaling cascade." (PMID 31462898, 2019). "NEDD9 is also involved in canonical Wnt/β-catenin pathway-mediated colonic cell migration and cancer progression." (PMID 31019460, 2019). "Neural precursor cell-expressed developmentally downregulated protein 9 (NEDD9) is a well-known scaffolding molecule for signaling proteins and it plays a significant role in cancer development." (PMID 31462898, 2019). "NEDD9 regulates tyrosine-kinase-based signaling complexes involved in multiple actions such as cell adhesion, migration and apoptosis, affecting cancer metastasis." (PMID 30303964, 2018). "Increased aldehyde dehydrogenase (ALDH) activity and CD133-positive cells were observed in HCC cells with high expression of NEDD9, corresponding to greater sphere formation in cancer stem cells (CSCs)." (PMID 27974675, 2017). "This was, however, an unexpected finding since NEDD9 confers aggressiveness in most cancer types studied so far." (PMID 29100287, 2017). "Since EMT promotes malignant cell invasion into the tissues surrounding most carcinomas, we overexpressed or suppressed NEDD9 in HCC cell lines MHCC97H and Li-7, which have a highly aggressive phenotype (data not shown)." (PMID 27974675, 2017).